H2AC14 (H2A clustered histone 14)
Description:
Core component of nucleosome. Nucleosomes wrap and compact DNA into chromatin, limiting DNA accessibility to the cellular machineries which require DNA as a template. Histones thereby play a central role in transcription regulation, DNA repair, DNA replication and chromosomal stability. DNA accessibility is regulated via a complex set of post-translational modifications of histones, also called histone code, and nucleosome remodeling.
Synonyms: H2AFE; HIST1H2AJ; H2A/E; dJ160A22.4
Tractability: PROTAC: UniProt records ubiquitination sites on it; ubiquitination databases record sites on it.
Gene: Protein-coding gene on chromosome 6 (27,814,302 to 27,814,777, reverse strand). Ensembl gene ENSG00000276368.
Subcellular location: Nucleus; Chromosome
Subcellular location (Human Protein Atlas): Nucleoplasm
Pathways (Reactome):
Gene expression (Transcription): B-WICH complex positively regulates rRNA expression; DNA methylation; ERCC6 (CSB) and EHMT2 (G9a) positively regulate rRNA expression; MLL4 and MLL3 complexes regulate expression of PPARG target genes in adipogenesis and hepatic steatosis; NoRC negatively regulates rRNA expression; PRC2 methylates histones and DNA; RNA Polymerase I Promoter Escape; RNA Polymerase I Promoter Opening; RUNX1 regulates genes involved in megakaryocyte differentiation and platelet function; RUNX1 regulates transcription of genes involved in differentiation of HSCs; Regulation of endogenous retroelements by KRAB-ZFP proteins; Regulation of endogenous retroelements by Piwi-interacting RNAs (piRNAs); Regulation of endogenous retroelements by the Human Silencing Hub (HUSH) complex; SIRT1 negatively regulates rRNA expression; Transcriptional regulation by small RNAs
Chromatin organization: CHD1 and CHD2 subfamily; CHD6, CHD7, CHD8, CHD9 subfamily; ChAHP complex assembly; HATs acetylate histones; HDACs deacetylate histones; Interaction of NuRD complexes with transcription factors; NuRD complex assembly; RMTs methylate histone arginines
Cell Cycle: Condensation of Prophase Chromosomes; Deposition of new CENPA-containing nucleosomes at the centromere; Inhibition of DNA recombination at telomere; Packaging Of Telomere Ends
DNA Repair: Cleavage of the damaged purine; Cleavage of the damaged pyrimidine; Recognition and association of DNA glycosylase with site containing an affected purine; Recognition and association of DNA glycosylase with site containing an affected pyrimidine
Disease: Defective pyroptosis; Dengue Virus-Host Interactions; HCMV Early Events; HCMV Late Events
Metabolism of proteins: Amyloid fiber formation; Metalloprotease DUBs; UCH proteinases; Ub-specific processing proteases
Signal Transduction: Activated PKN1 stimulates transcription of AR (androgen receptor) regulated genes KLK2 and KLK3
and 15 more pathways
Gene Ontology:
Molecular function: protein binding; structural constituent of chromatin; DNA binding; protein heterodimerization activity
Biological process: heterochromatin formation
Cellular component: extracellular exosome; nucleoplasm; nucleus; nucleosome; chromosome
Genetic constraint (gnomAD): Loss-of-function variants: 6 observed, 5.16 expected, observed/expected ratio (o/e) 1.16, 90% interval 0.62 to 1.87. That is too few expected variants to judge how well the gene tolerates losing a copy. Missense variants: 136 observed, 167.1 expected, observed/expected ratio (o/e) 0.81, 90% interval 0.71 to 0.94. Synonymous variants: 121 observed, 75.45 expected, observed/expected ratio (o/e) 1.6, 90% interval 1.38 to 1.86.
Homologues: Orthologues: chimpanzee H2AC14 (100% identical), macaque H2AC14 (100% identical), Drosophila melanogaster His2A:CG31618 (87% identical), Drosophila melanogaster His2A:CG33808 (87% identical), Drosophila melanogaster His2A:CG33814 (87% identical), Drosophila melanogaster His2A:CG33817 (87% identical), Drosophila melanogaster His2A:CG33820 (87% identical), Drosophila melanogaster His2A:CG33823 (87% identical), Drosophila melanogaster His2A:CG33826 (87% identical), Drosophila melanogaster His2A:CG33829 (87% identical), Drosophila melanogaster His2A:CG33832 (87% identical), Drosophila melanogaster His2A:CG33835 (87% identical), and 10 more. Paralogues in human: H2AC11 (99% identical), H2AC12 (99% identical), H2AC13 (99% identical), H2AC15 (99% identical), H2AC16 (99% identical), H2AC17 (99% identical), H2AC7 (98% identical), H2AC18 (98% identical), H2AC19 (98% identical), H2AC4 (98% identical), H2AC6 (98% identical), H2AC8 (98% identical), and 15 more.
Diseases named in the same sentence as H2AC14 in open-access papers:
H2AC14 is named in the same sentence as 7 diseases in open-access papers, as found by Europe PMC text mining. Sharing a sentence is not in itself a finding about the gene and the disease.
H2AC14 shares sentences with these, for which no sentence is quoted: systemic lupus erythematosus (2 papers); bipolar disorder (1); breast carcinoma (1); infection (1); osteosarcoma (1); ovarian carcinoma (1); skin cutaneous melanoma (1).